LEP (leptin)
Diseases named in the same sentence as LEP in open-access papers (continued):
Sharing a sentence is not in itself a finding about the gene and the disease.
tumor (continued). "We performed an immunohistochemistry assay on adipose tissue far away (hRATfT) and near (hRATnT) tumor cells, in order to measure versican, adiponectin and leptin levels and localization in both tissue samples." (PMID 29212223, 2017). "Leptin also promoted tumor growth and lymph node metastasis in a subcutaneous and orthotopic PC xenograft model." (PMID 27999190, 2017). "Given the antagonism between ADIPO and LEP signaling pathways we evaluated the ADIPO:LEP ratio as an indicator of the tumor growth microenvironment." (PMID 28873415, 2017). "The ADIPO:LEP ratio was still found to be a predictor of the proliferative tumor growth microenvironment created by the adipose tissue." (PMID 28676553, 2017). "Our results show that indeed adipose tissue taken near the tumor secretes (among other factors), increased levels of leptin, which has been shown to have tumorigenic properties." (PMID 29212223, 2017). "The patients with high tumor stage (III-IV) had higher leptin-LepRb mRNA levels than that with low tumor stage (I-II)." (PMID 28316984, 2017). "Many investigations have illustrated the function of leptin in tumor cells proliferation, movement, invasion and apoptosis inhibition." (PMID 29121911, 2017). "Some other reports have examined leptin function in several tumor development risks, but the results are controversial." (PMID 29121911, 2017). "Further, the patients with high tumor stage tend to have higher leptin-LepRb mRNA levels than that with low tumor stage." (PMID 28316984, 2017). "The tumor growth-promoting effects of leptin were also confirmed by measuring tumor size, tumor weight, and tumor volume." (PMID 29312618, 2017). "MDA-MB-231 cells and pre-adipocytes/adipocytes were inoculated into nude mice, the tumor volume was measured, and the protein expression of key molecules in leptin signaling pathway was detected." (PMID 28415788, 2017). "To examine the effect of altering the ADIPO:LEP ratio alone on tumor growth environment, we increased this ratio by adding 18 nM gADIPO to the “obese” ZDF co-cultures." (PMID 28873415, 2017). "Leptin induces macrophage recruitment to the tumor microenvironment by stimulating aromatase and estrogen receptor (ER) α in the macrophages." (PMID 27588409, 2016). "A component of safer diets in the future will be inclusion of factors that reduce the contribution of ciculating endogenous leptin to tumor biology." (PMID 27050378, 2016). "Depletion of mouse macrophage by Clophosome®-clodronate liposome and injection of anti-mouse IL-8 neutralizing antibodies in the xenograft tumor significantly attenuated those leptin-mediated stimulations (All P < 0.05)." (PMID 27588409, 2016). "From day 15 to day 30 after leptin injection, mice in the leptin group developed the largest tumor volume (P < 0.05)." (PMID 27588409, 2016). "Herein we have identified the adipokine leptin and relevant kinases that correlate with tumor latency and pre-neoplastic lesion formation in the mammary gland." (PMID 27042159, 2016). "In fact, AT is recognized now as potent endocrine organ by secreting pro-inflammatory cytokines (such as TNF-α and IL-6) and adipokines (such as leptin) in the tumor microenvironment." (PMID 27066006, 2016). "Accumulating evidences have shown that adipokines secreted from adipocytes contributes to tumor development, especially leptin." (PMID 27863383, 2016). "Leptin, acting in an autocrine, endocrine and paracrine manner, influences many aspects of breast tumorigenesis from initiation and primary tumor growth to metastatic progression." (PMID 26899873, 2016). "TGF-β is one of several inflammatory cytokines that can modulate the synthesis and secretion of leptin from adipose and tumor cells, thus linking leptin with the inflammatory response." (PMID 27472371, 2016).
tumor (continued). "The cellular composition, metabolites, kinases, growth factors including adipokines such as leptin, and modifications to the extracellular matrix in the microenvironment have critical effects on tumor biology." (PMID 27042159, 2016). "The decreased IGF-1 and leptin and the increased adiponectin levels in genetically engineered models reflect the significantly superior tumor inhibition of ICR compared to CCR." (PMID 27653140, 2016). "Recently, we have identified leptin as one of the most important molecular player that mediates CAF effects in influencing tumor cell behavior." (PMID 26899873, 2016). "Herein, we demonstrated, for the first time, that the synthetic FXR agonist GW4064, inhibiting leptin signaling, affects the tumor-promoting activities of CAFs in breast malignancy." (PMID 26899873, 2016). "Compared with PBS injection, leptin injection significantly increased tumor mass on day 30 (P < 0.01), worsened survival (P < 0.05), exacerbated pulmonary metastasis (P < 0.01), and elevated the expression of IL-8 and Ki67 in the tumor tissue (P < 0.01)." (PMID 27588409, 2016). "A number of genes encoding protein mediators were uniformly expressed by tumor cells and/or TAMs (e.g. IL8, KITLG, LEP), but median expression of the corresponding receptor genes was extremely low in both cell types." (PMID 27215396, 2016). "obASCs not only contribute to the primary tumor growth, but these cells also enhance metastasis through a leptin-mediated pathway(s) involving SERPINE1 and MMP-2." (PMID 26286584, 2015). "We were able to consistently confirm in vivo in the tumor microenvironment our ex vivo results where we found Ob-R downregulation in peritoneal macrophages and TAMs upon their pre-treatment with leptin." (PMID 25599228, 2015). "Collectively, the findings presented here show that HNK treatment inhibits tumor progression in hyperleptinemic (high-leptin) obese conditions and abrogate activation of leptin-signaling molecules." (PMID 26036628, 2015). "Leptin administration also accelerated tumor growth in BALB/c nude mice, which was found to be autophagy dependent." (PMID 25704884, 2015). "In AEG tumor tissues alone HGF and Leptin were found to be associated with patients’ survival (p = 0.028 and p = 0.034)." (PMID 25885021, 2015). "Based on these results, autophagy seems to play a crucial role in leptin-induced tumor growth via stimulating cell cycle, as well as regulating apoptotic process." (PMID 25704884, 2015). "The immunohistochemical assessment of tumor proliferation showed higher Ki-67 in the leptin-treated group as compared with the control group." (PMID 26036628, 2015). "Similar to the tumor volume, the tumor weight was increased by 81.6% in the leptin-overexpressing tumors." (PMID 25948792, 2015). "Further studies with isolated NK cells and co-cultures with tumor cells are required to investigate the contribution of leptin and other adipocytokines on NK cell functions." (PMID 26217516, 2015). "Leptin is reported to be anti-apoptotic in tumor cells, consistent with an upregulation of NFκB and STAT3 anti-apoptotic transcription factors." (PMID 25599228, 2015). "Macrophages were exposed to the adipocyte and tumor paracrine factors leptin, CCL2 and lauric acid (alone or in combinations)." (PMID 25599228, 2015). "We used tumor samples from the same study to evaluate the effect of HNK on leptin-induced mesenchymal markers by RT-PCR analysis." (PMID 26359358, 2015). "Immunohistochemical analysis showed that tumors from leptin-treated mice exhibited higher number of tumor cells showing increased expression of MTA1, Wnt1, β-catenin and cyclin D1 as compared to tumors from vehicle-treated group." (PMID 26036628, 2015). "First of all, leptin and adiponectin receptor density in EC tumor tissue correlates directly for leptin and inversely for adiponectin receptors, with regional lymph nodes involvement." (PMID 28031919, 2015).
tumor (continued). "The ability of peptide LDFI to inhibit leptin-mediated cell growth was also evaluated using anchorage-independent growth assays, which better reflect in vivo three-dimensional tumour growth." (PMID 25721149, 2015). "Data presented in this study clearly demonstrate for the first time that leptin-induced autophagic process plays an important role in tumor growth via attenuation of apoptosis." (PMID 25704884, 2015). "AdipoR1, adiponectin, Ob-R and leptin were higher on score and area of staining in the tissues adjacent to the tumor than the tumor tissue." (PMID 26431176, 2015). "In vivo analyses of tumor xenografts from leptin-treated mice and obese-mice (physiologically hyperleptinemic) provide further evidence of the involvement of miR-34a, Wnt1-MTA1-β-catenin axes." (PMID 26036628, 2015). "Intraperitoneal injection with leptin promoted tumor growth in xenograft model consistent with the previous reports, also evidenced by increase in tumor volume and tumor weight." (PMID 25704884, 2015). "Ratio between adiponectin and leptin levels were indifferent comparing either of the tissues (0.89±0.96 in the tumor tissue and 1.03±095 in the tissue adjacent to the tumor, p = ns)." (PMID 26431176, 2015). "Short-term leptin administration resulted in slightly improved levels of NK-cell-tumor-cell-conjugates as compared to the vehicle treated controls both in normal weight and obese subjects." (PMID 26217516, 2015). "Knockdown of leptin significantly reduced tumor volume and decreased the number of metastatic lesions to the lung and liver." (PMID 26286584, 2015). "Leptin induced EPCs and NO production has been shown to play critical roles in melanoma tumour growth induction." (PMID 25650072, 2015). "It will be important to determine the role of leptin in a larger panel of human cell lines as well as patient derived xenografts in order to fully understand its effect on human tumor progression." (PMID 25919692, 2015). "Tumors from HNK+leptin treatment group showed very low percentage of tumor cells showing expression of MTA1, Wnt1, β-catenin and cyclin D1 providing physiological relevance to our in vitro findings." (PMID 26036628, 2015). "When determining intensity alone adiponectin, PGF2α, F2-isoprostanes levels were higher in the tissues adjacent to the tumor than the tumor tissue whereas AdipoR2, leptin, and COX-2 levels were higher in the tumor tissues." (PMID 26431176, 2015). "Regarding the patients with SD, patients with exacerbated tumor burden (5/9) showed an obvious reduction in serum leptin levels, while patients in remission (4/9) showed an increase in serum leptin." (PMID 24932291, 2014). "Other explanations proposed relate to metformin’s well-known effects on cholesterol, leptin, insulin levels and adiponectin, suggesting that some metabolic changes account for a reduction in tumor growth." (PMID 25215935, 2014). "Comparing the CRD and RD groups, it can be suggested that the main tumor regressive effects of CRD are associated with decreased production of insulin, IGF-1 and leptin." (PMID 25026276, 2014). "On the other hand, the mice group on CRD exhibited the least tumor burden associated with a significant reduction in levels of insulin, IGF-1, leptin, MCP-1, VEGF and IL-6." (PMID 25026276, 2014). "Within the context of the tumor microenvironment, adiponectin and leptin counter-regulate each other and exert opposing effects." (PMID 25360510, 2014). "An important factor released from adipose tissue impacting tumor angiogenesis is leptin, an adipokine, that promoted the proliferation and angiogenic differentiation of endothelial cells in vitro and in vivo." (PMID 24202338, 2013). "In the present study, leptin and OBR expression levels were found to be associated with PTC tumor size, which is similar to the observations of two previous studies." (PMID 23425972, 2013).
tumor (continued). "Results of this meta-analysis are consistent with a variety of observational and experimental studies that support a role for leptin in tumor progression." (PMID 23826274, 2013). "Additional research is needed to establish the importance of leptin, insulin and related factors to the paracrine control of tumor angiogenesis." (PMID 24202338, 2013). "In summary, our observations have added to the evidence that leptin and OBRs are expressed in PTC and their expression is associated with each other and with PTC tumor size." (PMID 23425972, 2013). "The expression of OBRs was observed in the tumor cell membrane and/or cytoplasm, with a positive rate of 73.7% (56/76), while leptin was expressed in the tumor cell cytoplasm in 55 of 76 cases (72.4%)." (PMID 23425972, 2013). "OBR expression was observed in tumor cell membrane and/or cytoplasm with a positive rate of 73.7% (56/76), while leptin was expressed in tumor cell cytoplasm in 55 of 76 cases (72.4%)." (PMID 23425972, 2013). "Obesity increases serum leptin levels, which acts as a growth and survival factor for colon epithelial cells and increases tumor growth in the AOM model." (PMID 23737651, 2013). "Leptin attracted macrophages and other inflammatory cells expressing OB-R to the tumor microenvironment, which in turn promotes angiogenesis." (PMID 24202338, 2013). "We further examined the direct role of leptin in tumor cell proliferation using a leptin-neutralizing antibody." (PMID 23272114, 2012). "Leptin expression levels in tumor extracts didn’t show any significant differences between SE and EE mice." (PMID 23272114, 2012). "Animal studies have shown that circulating leptin levels are decreased in the setting of tumor-induced cachexia, as expected given the decrease in fat mass seen in this setting." (PMID 22518191, 2012). "The pleiotrophic effects of leptin, namely in tumor development and progression are mediated by its receptor." (PMID 22792137, 2012). "While leptin is an apparent growth factor for BC that is elevated in BC patients, its mechanism of tumor promotion remains equivocal." (PMID 23369448, 2012). "Conversely, db/db mice, which express leptin but have a mutation in the leptin receptor, displayed small tumors, suggesting that leptin has a tumor-suppressive role." (PMID 22853690, 2012). "Leptin and ObR expression are correlated with the grade of the tumor, differentiation, and microvessel density." (PMID 22263109, 2012). "In these models, positive mental stimulation through environmental enrichment decreased leptin secretion and improved tumor outcome." (PMID 22263109, 2012). "Leptin does this through stimulation of cellular pathways that are also advantageous for tumor growth and recurrence: antiapoptosis, proliferation, angiogenesis, and migration." (PMID 22263109, 2012). "Nevertheless, plasma leptin levels are significantly reduced in EE tumor-bearing mice even if we were unable to explain this down-regulation or exactly when it occurred between tumor cell administration and animal sacrifice." (PMID 23272114, 2012). "One of the most important member of such adipokines family is leptin, which increases cell proliferation in several tumor cell lines, enhances endothelial cell migration in vitro, and has been suggested to be an angiogenic/vasculogenic factor." (PMID 21338489, 2011). "Others did not observe any significant differences for the fasting serum leptin levels in patients according to pTNM staging although a role for the leptin receptor is discussed in relation with the tumor immune response." (PMID 21254741, 2010). "We previously reported that the blockade of leptin actions in mice hosting syngeneic MTs delayed tumor onset and reduced tumor growth." (PMID 19531256, 2009). "The leptin tumor-promoting effects are probably direct (cell proliferation and survival) and indirect via the regulation of molecules involved in tumor growth." (PMID 19531256, 2009).
tumor (continued). "Little is known, however, about the exact mechanism(s) by which leptin contributes to tumor progression." (PMID 19531256, 2009). "In a similar way, PEG-LPrA2 treatment reduced the levels of human leptin within MDA-MB231 BC xenografts but tumor levels of mouse leptin were similar between treated and controls." (PMID 19531256, 2009). "Leptin signaling regulates the expression of angiogenic and pro-proliferative factors in BC and tumor stroma." (PMID 19531256, 2009). "We herein review the latest tumor biological findings on the role of the most prominent adipocytokines leptin and adiponectin, which are secreted by fat cells, and which are involved in leukocyte migration, tumor growth, invasion and metastasis." (PMID 20030801, 2009). "In summary, this review clarifies the enormous wide range of efficacy adipocytokines such as leptin and adiponectin do have in vivo on leukocytes and tumor cells besides their already known physiological functions." (PMID 20030801, 2009). "Taken together, these results suggest that the balance in the concentrations of adipocytokines such as leptin and adiponectin ultimately determines the consequences of these substances for the immune response and the tumor progression." (PMID 20030801, 2009). "These factors, including TNF-α, IL-1α, IL-1β, VEGF, and fibroblast growth factor 2 (FGF-2), raise leptin levels and promote tumor growth and differentiation." (PMID 19017403, 2008). "Leptin mRNA levels were dramatically decreased (by 33-fold, P<0.01) in tumour-bearing mice, but were only moderately reduced (by four-fold, P<0.01) in pair-fed mice as compared with controls." (PMID 17047651, 2006). "Interestingly, tirzepatide, which exhibits partial anti-inflammatory activity, was reported to reduce tumor growth rates by ∼50 %, largely through lowering circulating leptin, a key driver of chronic low-grade inflammation." (PMID 41551882, 2026). "Adipokines such as chemerin, resistin, leptin, and apelin contribute to tumour progression." (PMID 42135288, 2026). "Moreover, LEP is demonstrated to be involved in various tumour progression also through glycolysis‐related processes." (PMID 41474013, 2026). "The mechanism underlying these processes is of dysregulation of PRAT’s secretion of adipokines and pro-inflammatory cytokines, such as leptin, adiponectin, chemerin, apelin, omentin-1, vistatin, nesfatin-1, and other pro-inflammatory cytokines, modulated by tumor cells." (PMID 40227577, 2025). "Leptin secreted from adipocytes activates JAK-STAT3 signaling pathway in breast cancer stem cells (BCSCs), which heightens FAO via STAT3 association with CPT2 promoter, contributing to tumor spheroid forming." (PMID 40290117, 2025). "In tumor tissues, leptin and ObR were expressed in the stromal cells of 72.2% and 18.2% of tumors, respectively, and a mean 81% and 87.6% of inflammatory mononuclear cells were also positive for leptin and ObR, respectively." (PMID 41150099, 2025). "In a mouse CRC model, combining exogenous leptin with anti-PD-1 further boosted tumor control and increased M1 macrophage polarization in the tumor, suggesting that leptin can fuel a more potent immune attack on the tumor in the presence of immune checkpoint blockade." (PMID 40519904, 2025). "In murine breast cancer models, DCs stimulated with leptin (particularly when combined with LPS) reduced tumor-promoting gene expression, including matrix metalloproteinase 9 (MMP9), CCL5, and vascular endothelial growth factor (VEGF), and decreased IL-6 secretion." (PMID 41516046, 2025). "In addition to FFAs, increased release of cytokines such as IL‐6 and leptin by adipocytes in the TME can also lead to tumor immune escape, as observed in prostate cancer cells that are resistant to the cytotoxic action of NK cells." (PMID 39496581, 2025). "Moreover, data suggests that leptin can play other roles in immune response, tumor infiltration and metastasis." (PMID 39980561, 2025).